ST6GALNAC3 (ST6 N-acetylgalactosaminide alpha-2,6-sialyltransferase 3)
Description:
Transfers the sialyl group (N-acetyl-alpha-neuraminyl or NeuAc) from CMP-NeuAc to the GalNAc residue on the NeuAc-alpha-2,3-Gal-beta-1,3-GalNAc sequence of glycoproteins and glycolipids forming an alpha-2,6-linkage. Produces branched type disialyl structures by transfer of a sialyl group onto a GalNAc residue inside the backbone core chains. ST6GalNAcIII prefers glycolipids to glycoproteins, predominantly catalyzing the biosynthesis of ganglioside GD1alpha from GM1b. GD1alpha is a critical molecule in the communication and interaction between neuronal cells and their supportive cells, particularly in brain tissues, and functions as an adhesion molecule in the process of metastasis (By similarity). Sialylation of glycoproteins or glycosphingolipids is very important in tumor development, neuronal development, nerve repair, immunological processes and regulation of hormone sensitivity.
Synonyms: ST6GalNAcIII; SIAT7C; PRO7177; STY
Tractability: Antibody: UniProt predicts a signal peptide or a membrane-spanning region.
Gene: Protein-coding gene on chromosome 1 (76,074,746 to 76,634,603, forward strand). Ensembl gene ENSG00000184005.
Subcellular location: Golgi apparatus membrane
Subcellular location (Human Protein Atlas): Nucleoplasm
Pathways (Reactome):
Disease: Maturation of protein 3a; Maturation of spike protein
Metabolism of proteins: Sialic acid metabolism; Termination of O-glycan biosynthesis
Gene Ontology:
Molecular function: protein binding; sialyltransferase activity; alpha-N-acetylgalactosaminide alpha-2,6-sialyltransferase activity; alpha-N-acetylneuraminyl-2,3-beta-galactosyl-1,3-N-acetyl-galactosaminide 6-alpha-sialyltransferase activity
Biological process: glycoprotein metabolic process; glycosphingolipid metabolic process; glycosylceramide metabolic process; ganglioside biosynthetic process; oligosaccharide metabolic process; viral protein processing; glycolipid metabolic process; glycoprotein biosynthetic process
Cellular component: Golgi membrane
Genetic constraint (gnomAD): Loss-of-function variants: 20 observed, 29.24 expected, observed/expected ratio (o/e) 0.68, 90% interval 0.48 to 0.99. The upper end of that interval is the gene's LOEUF score, 0.99, which puts it in group 4 of 6, group 1 being the genes least tolerant of losing a copy. Missense variants: 339 observed, 380.33 expected, observed/expected ratio (o/e) 0.89, 90% interval 0.81 to 0.98. Synonymous variants: 122 observed, 132.63 expected, observed/expected ratio (o/e) 0.92, 90% interval 0.79 to 1.07.
Homologues: Orthologues: chimpanzee ST6GALNAC3 (99% identical), macaque ST6GALNAC3 (98% identical), dog ST6GALNAC3 (97% identical), guinea pig ST6GALNAC3 (97% identical), pig ST6GALNAC3 (96% identical), rat St6galnac3 (86% identical), mouse St6galnac3 (85% identical), tropical clawed frog st6galnac3 (73% identical), zebrafish st6galnac3 (61% identical). Paralogues in human: ST6GALNAC4 (43% identical), ST6GALNAC6 (37% identical), ST6GALNAC5 (35% identical), ST6GAL2 (20% identical), ST3GAL1 (18% identical), ST3GAL4 (18% identical), ST6GALNAC2 (18% identical), ST6GALNAC1 (17% identical), ST3GAL6 (17% identical), ST3GAL2 (17% identical), ST3GAL3 (17% identical), ST6GAL1 (16% identical), and 2 more.
Diseases named in the same sentence as ST6GALNAC3 in open-access papers:
ST6GALNAC3 is named in the same sentence as 10 diseases in open-access papers, as found by Europe PMC text mining. Sharing a sentence is not in itself a finding about the gene and the disease. The quoted sentences say what the papers report.
bladder cancer (1 paper, 2023). "Studies have shown that ST6GALNAC3 has prognostic significance in bladder cancer, liver cancer and lung cancer." (PMID 37138287, 2023).
breast carcinoma (1 paper, 2018). "We performed bioinformatics analysis of the data from the miRDB, Targetscan, Pictar, and miRanda websets to explore the molecular mechanism of miR-27a as an oncogenic molecule in breast cancer, and found that six genes are overlapped, namely TMEM170B, GPAM, PPAP2B, ST6GALNAC3, EYA1, and PPARG." (PMID 29367600, 2018).
COVID-19 (1 paper, 2021). A disease caused by infection with severe acute respiratory syndrome coronavirus 2. "It remains, however, to be determined whether ST6GALNAC3, generally expressed at high levels in renal cell cancer, plays a significant role in COVID-19 pathogenesis." (PMID 33924631, 2021).
gastric cancer (1 paper, 2023). A primary or metastatic malignant neoplasm involving the stomach. "We also explored the expression of ST6GALNAC3 in various gastric cancer cell lines." (PMID 37138287, 2023).
tumor (5 papers, 2021 to 2024). "Our study found that ST6GALNAC3 may be a therapeutic target related to lipid metabolism in tumor cells." (PMID 37138287, 2023). "Finally, we measured the levels of St3Gal1, St6Gal1, and St6GalNac3 in the tumor explants." (PMID 39104719, 2024). "ST6GALNAC3 may be a therapeutic target related to lipid metabolism in tumor cells." (PMID 37138287, 2023). "Transcriptome and survival analyses revealed four potential tumor suppressor genes including KCNIP4, CACNA1C, PACRG, and ST6GALNAC3." (PMID 35321246, 2022). "For the four newly discovered tumor suppressor genes, i.e., KCNIP4, CACNA1C, PACRG, and ST6GALNAC3, previous studies have proved their regulatory effect in tumors." (PMID 35321246, 2022). "According to the changes of the expression status of differential molecules between the two networks, we identified the top 10 differential mRNAs (PRKAA2, NLGN4X, ST6GALNAC3, DGAT1, TRIB1, GRPR, and MLLT11) and lncRNAs (n339695, n378130, and n410438) in the tumor–endothelium interaction." (PMID 33681194, 2021).
cancer (2 papers, 2018 to 2022). A tumor composed of atypical neoplastic, often pleomorphic cells that invade other tissues. "In contrast, a limited number of genes are predominantly downregulated throughout all cancer types, such as ST6GALNAC6, ST6GALNAC3, GALNT16 and MAN1C1." (PMID 36009354, 2022).
ST6GALNAC3 also shares sentences with these, for which no sentence is quoted: liver cancer (1 paper); lung carcinoma (1); renal carcinoma (1); renal cell cancer (1).